KRTAP1-3 (keratin associated protein 1-3)
Description:
In the hair cortex, hair keratin intermediate filaments are embedded in an interfilamentous matrix, consisting of hair keratin-associated proteins (KRTAP), which are essential for the formation of a rigid and resistant hair shaft through their extensive disulfide bond cross-linking with abundant cysteine residues of hair keratins. The matrix proteins include the high-sulfur and high-glycine-tyrosine keratins.
Synonyms: KAP1.2; KAP1.3; KAP1.9; KAP1.6; KAP1.8A; KAP1.8B; KRTAP1.3
Tractability: No criterion of Open Targets' tractability assessment is met for any kind of drug.
Gene: Protein-coding gene on chromosome 17 (41,033,884 to 41,034,874, reverse strand). Ensembl gene ENSG00000221880.
Pathways (Reactome):
Developmental Biology: Keratinization
Gene Ontology:
Molecular function: protein binding; structural constituent of skin epidermis
Cellular component: cytosol; keratin filament
Genetic constraint (gnomAD): Loss-of-function variants: 11 observed, 14.61 expected, observed/expected ratio (o/e) 0.75, 90% interval 0.47 to 1.25. The upper end of that interval is the gene's LOEUF score, 1.25, which puts it in group 5 of 6, group 1 being the genes least tolerant of losing a copy. Missense variants: 176 observed, 210.4 expected, observed/expected ratio (o/e) 0.84, 90% interval 0.74 to 0.95. Synonymous variants: 74 observed, 71.58 expected, observed/expected ratio (o/e) 1.03, 90% interval 0.86 to 1.25.
Homologues: Orthologues: chimpanzee KRTAP1-3 (98% identical), mouse Krtap1-5 (48% identical), rat Krtap1-5 (47% identical). Paralogues in human: KRTAP1-1 (95% identical), KRTAP1-5 (92% identical), KRTAP1-4 (66% identical), KRTAP4-12 (42% identical), KRTAP4-6 (41% identical), KRTAP4-11 (40% identical), KRTAP4-3 (40% identical), KRTAP4-9 (38% identical), KRTAP4-4 (37% identical), KRTAP4-5 (37% identical), KRTAP9-1 (37% identical), KRTAP9-2 (37% identical), and 35 more.
Diseases named in the same sentence as KRTAP1-3 in open-access papers:
KRTAP1-3 is named in the same sentence as 11 diseases in open-access papers, as found by Europe PMC text mining. Sharing a sentence is not in itself a finding about the gene and the disease. The quoted sentences say what the papers report.
rectal cancer (1 paper, 2022). A primary or metastatic malignant neoplasm that affects the rectum. "KRTAP13-2 encodes Keratin Associated Protein 13-2, which was also downregulated in rectal cancer." (PMID 36293321, 2022).
KRTAP1-3 also shares sentences with these, for which no sentence is quoted: embolic strokes (2 papers); cancer (1); cardiovascular disease (1); colorectal tumor (1); heart failure (1); Hypertension (1); hypertensive disorder (1); lung carcinoma (1); Stroke (1); tumor (1).